CD14 (CD14 molecule)
Diseases named in the same sentence as CD14 in open-access papers (continued):
Sharing a sentence is not in itself a finding about the gene and the disease.
lung cancer (continued). "used a CD14+CD36+PANK+ macrophage-lung cancer fusion hybrid signature, developed through a combination of FACS isolation and RNA-seq, to assess whether macrophage-cancer cell fusion hybrids could be found in peripheral blood of patients with lung cancer." (PMID 37427108, 2023). "Recently, data have emerged indicating that generating local immunosuppression may not be the initial event connecting CD14+ TME cells with poor patient outcomes in early-stage lung cancer." (PMID 36139660, 2022). "In recent studies, a novel subset of MDSCs were identified based on the presence of CD14 expression but the absence of human leukocyte antigen (HLA)-DR expression (CD14+HLA-DR−) in the peripheral blood of cancer patients, including those with lung cancer and head and neck SCC." (PMID 25238263, 2014). "We revealed that the elevated levels of CD14− CD16+ monocytes, known as nonclassical monocytes or patrolling monocytes (PMo), have a protective role in lung cancer development." (PMID 38408977, 2024). "Importantly, immune cell infiltrates of resected tumors from patients with MPR contained fewer CD16+ neutrophil granulocytes, CD14+ monocytes and CD4+CD25+ regulatory T cells compared with resected lung cancers without MPR." (PMID 38689060, 2024).
ovarian carcinoma (41 papers, 2000 to 2025). A malignant neoplasm originating from the surface ovarian epithelium. "IDO is a key regulator of Treg/Th17 immunity, and is a known mechanism of immune suppression by tumor-associated ascites CD14+ myeloid cells from ovarian cancer patients." (PMID 26343197, 2015). "The CD14 is a lipopolysaccharide receptor, and isinvolved in the stimulation of cell proliferation.Similar association of CD14 primitive MDC with proliferating epithelial cellswas detected in ovarian cancers (see later)." (PMID 20195382, 2009). "Similarly, we discovered that monocytes (such as HLA DR on CD14+ CD16-monocyte, HLA DR on CD14+ monocyte, and HLA DR on monocyte) were linked to a lower risk of ovarian cancer." (PMID 38746677, 2024). "Research has elucidated that ascites-derived IL-6 and IL-10 amplify CD14+ HLA-DR−/low MDSCs in ovarian cancer patients." (PMID 41029721, 2025). "We found that CD14+ cells isolated from human ovarian cancer ascites, which consist mostly of macrophages had minimal glycogen stores." (PMID 39424955, 2024). "Single-cell RNA seq of metastatic omental tumor of ovarian cancer identified a CD163+CD204+ cluster with high CD14 and CD16 expression and a NR1H2+ cluster in macrophages of all 6 cases." (PMID 37180125, 2023). "Circulating CD14+HLA-DRlo/− monocytic MDSCs as an immune suppressive subset have potential clinical relevance for epithelial ovarian cancer progression and HCC patients treated with trans-arterial radioembolization." (PMID 37443711, 2023). "For example, CD206 expression can be induced on CD14+ monocytes from peripheral blood cocultured with IL-6, one of the major cytokines upregulated in ovarian cancer ascites." (PMID 37180125, 2023). "FGF7 (antibody: HPA043605) and CD14 (antibody: HPA001887) have higher protein content in the tissues of ovarian cancer patients, the staining of IHC sections is deeper, and the results of CD14 are more obvious." (PMID 35735060, 2022). "Previous studies have shown that in ovarian cancer CD14+ cells can suppress T cell proliferation via IL-10." (PMID 34727230, 2022). "It has been reported that CD14+HLA-DR−/low MDSCs in the blood are increased in patients with ovarian cancer, and we obtained similar results in this study." (PMID 32487171, 2020). "To further characterize the immune infiltrate of ovarian cancer, we examined the phenotypes of infiltrating monocytes (CD14+) and mature APCs (CD11c+HLA-DRhigh)." (PMID 31892360, 2019). "Our study shows that supernatants of both WFDC1- and IL-17D-overexpressed, SORBS2-depleted ovarian cancer cells significantly reduced the amount of HLA-DRlo/neg CD14+ cells in vitro." (PMID 29548303, 2018). "Related, a recent study investigating peritoneal MØ/DC subsets within tumor ascites from patients with advanced ovarian cancer also identified CD14+ MØs and CD1c+ DCs, through a different flow-cytometric gating approach." (PMID 28065517, 2017). "Collectively, among the primary cells in ovarian cancer ascites, CD11b+CD14+ cells, which represent macrophages, induced cell invasion and the proliferation of ovarian cancer cells, at least partly, through the production of IL-6." (PMID 25658637, 2015). "In this study, we showed that IL-6 in ovarian cancer ascites is mainly derived from CD11b+CD14+CD206+ cells, M2-polalized macrophages, TAMs." (PMID 25658637, 2015). "Ovarian cancer ascites were collected from patients, and we found that primary CD11b+CD14+ cells, which were predominantly M2-polarized macrophages, are the major source of IL-6 production in an ovarian cancer microenvironment." (PMID 25658637, 2015). "CD14+ cells are abundant in human ovarian tumor ascites, and represent the major population of myeloid suppressor cells in ovarian cancer." (PMID 26343197, 2015).
ovarian carcinoma (continued). "In the Monocyte panel, reduction in the risk of ovarian cancer was associated with HLA DR on CD14+ CD16- monocyte (OR=0.823, 95%CI:0.74-0.916, P=3.381E-04), HLA DR on CD14+ monocyte (OR=0.819, 95%CI:0.734-0.913, P=3.365E-04), and HLA DR on monocyte (OR=0.824, 95%CI:0.73-0.93, P=0.002)." (PMID 38746677, 2024). "CD14+HLA-DR- monocytes have exquisite immunosuppressive activity and have been found in increases proportions in the tumor microenvironment of pancreatic, prostate, and ovarian cancers." (PMID 38899253, 2024). "Therefore, CD14 can effectively reflect the level of immune infiltration in patients with ovarian cancer." (PMID 35735060, 2022). "However, conditioned media from either WFDC1 or IL-17D overexpressed, SORBS2-depleted ovarian cancer cells significantly reduced the amount of HLA-DRlo/neg CD14+ cells." (PMID 29548303, 2018). "In addition, BDCA1+CD14+ cells were also found in inflammatory tumor ascites from ovarian cancer patients." (PMID 30235890, 2018). "In order to investigate whether plinabulin induces M1 polarization of human TAMs, we FACS sorted CD11b+CD14+ cells from two tumor digests derived from ovarian cancer patients (predominantly of the M2 phenotype), and treated them with plinabulin prior to staining with CTV." (PMID 33747968, 2021). "We have previously shown that TAM in ovarian cancer ascites can be stratified into subsets based on the expression of the surface markers CD163 and CD206 (encoded by the MRC1 gene), both of which show a high degree of variance among patients (1–94% CD163+ or CD206+ of the CD14+ TAM population)." (PMID 29141914, 2018). "The majority (87.8%) of CD11b+CD14+ cells were CD-68, a surface marker of macrophages, and CD-206, a surface marker of positive M2-polarized macrophages, suggesting that IL-6 producing cells in ovarian cancer ascites are predominantly M2-polarized macrophages, TAMs." (PMID 25658637, 2015). "To explore the role of MDSCs in EOC, we assessed the frequencies of M-MDSCs (CD11b+CD33+CD14+) and PMN-MDSCs (CD11b+CD33+CD15+) in peripheral blood and tumor tissues from patients with benign and malignant ovarian tumors." (PMID 41029721, 2025). "The starting material for cell line BOC-78 was ovarian cancer ascites fluid (sample 22-78-Ascites), consisting of mostly CD45+ inflammatory immune cells, including CD3+ T and CD19+ B lymphocytes, CD14+ monocyte/macrophages and CD56 NK cells." (PMID 39086481, 2024). "For miRNA transcriptome analysis, two primary ovarian cell clones with CD24-low (CD14.2) and CD24-high (C4) expression were obtained from an ovarian cancer patient." (PMID 38360723, 2024). "The overexpression of PGE2 in the microenvironment of ovarian cancer also induces the production of CXCL12 (SDF1), thereby enhances the migration of CD11b+CD14+CD33+CXCR4+MDSCs to the ascites of patients with ovarian cancer." (PMID 34689842, 2021). "In order to further elucidate the properties of primary cells in ovarian cancer ascites, cells were sorted by FACS with anti-CD11b and CD14 antibodies." (PMID 25658637, 2015). "We reported the presence of a proangiogenic myeloid cell population, expressing numerous myeloid (CD14, CD45, CD11c, CD11b) and vascular (VE-Cadherin, CD31, CD146) surface markers, in ovarian cancer." (PMID 19545375, 2009). "Ovarian carcinoma PCF leucocyte profile differed from that in blood with respect to: (i) lower percentage of NK and CD8+and (ii) higher percentage of B and CD45RO+, CD14+and HLA-DR+cells." (PMID 10682675, 2000). "Both, FcεRI and the monocyte marker CD14, were expressed in HER2+ breast and ovarian cancers." (PMID 40074330, 2025). "IL-10 transcripts are present in CD14+ leukocytes in the malignant ascites of ovarian cancer patients but not in the CD14− fraction and are only present in the HLA-DR− and not the HLA-DR+ CD14+ population." (PMID 34727230, 2022).
ovarian carcinoma (continued). "IRG1 protein was detected in CD14+ monocytes from patients with ovarian carcinoma, but not in normal peripheral blood mononuclear cells (PBMCs)." (PMID 29920191, 2018). "Although the mechanisms by which IDO expression and function are regulated in ovarian tumor-associated CD14+ myeloid cells have not been elucidated, various regulatory pathways have been described in other settings, any or all of which could be important for immune regulation in ovarian cancer." (PMID 26343197, 2015). "CD14, and IGFBP2 have been previously assayed in serum from ovarian cancer patients." (PMID 19936259, 2009). "PPBP was a secreted protein found up-regulated in the mouse plasma, but not discovered in the ovarian cancer cell lines, while CD14 and NRCAM were cell surface proteins from the ovarian cancer cell lines, and were not quantified in mouse plasma." (PMID 19936259, 2009).
coronary artery disease (40 papers, 2012 to 2025). "Studies show that an increased proportion of CD14 + CD16+ monocytes is associated with more severe coronary artery disease (CAD)." (PMID 37238933, 2023). "Disease progression in coronary artery disease was previously associated with an increasing MMP-9/TIMP‐1 ratio in circulating CD14+ monocytes." (PMID 31932967, 2021). "We performed an integrated WGCNA and validated that TLR2 and CD14 were closely associated with the severity of coronary artery disease, plaque instability and the prognosis of heart failure after myocardial infarction." (PMID 33574831, 2020). "Functional polymorphisms of TLR-4, Asp299Gly and Thr399Ile, CD14 promoter area C260T polymorphism and plasma levels of soluble CD14 are studied in subjects with Coronary Artery Disease (CAD)." (PMID 29367560, 2016). "Increased numbers of Siglec-1+ CD14+ monocytes has been implicated in systemic sclerosis associated pulmonary hypertension, systemic sclerosis, and coronary artery disease." (PMID 24279613, 2013). "The proatherosclerotic activity of CD14+ monocytes has been shown during the progression of coronary heart disease." (PMID 40564110, 2025). "In CD14+ monocytes from coronary artery disease (CAD) patients, H3K9me3 and H3K27me3 levels at the MCP-1 promoter are reduced, leading to increased MCP-1 transcription and plasma concentrations." (PMID 41403695, 2025). "In this study, CD14+ monocytes were purified from 758 individuals (459 patients with coronary artery disease or myocardial infarction and 458 healthy individuals)." (PMID 33959712, 2021). "Both expression levels of TLR2 and CD14 were lowest in the normal group and were high in the population with coronary artery disease and acute coronary syndrome." (PMID 33574831, 2020). "Similar results were found in the CD14 group, but the expression level of CD14 in convalescence was still higher than that in the stable coronary heart disease group." (PMID 33574831, 2020). "The objective of this study was to evaluate the correlation between MCRF and various types of circulating mononuclear cells (CMCs) that express CD14+VEGFR-2+ and CD14+VEGFR-2+Tie2+ in patients with asymptomatic coronary artery disease." (PMID 26237060, 2013). "Interestingly, most of these pro-inflammatory genes like CCL5, CXCL10, CXCL9, CTSK, and CD14 have been previously reported to be elevated in the serum of patients with coronary artery diseases." (PMID 35488341, 2022). "A recent meta-analysis has suggested a possible association between the CD14 C260T polymorphism and ischemic heart disease risk in an East Asian population but not in European and Indian populations." (PMID 29367560, 2016). "Moreover, soluble CD14 levels correlated with mortality during the chronic phase of HIV infection, with baseline CD14 levels associated with a more rapid decline in CD4 cells and a higher risk of death from coronary heart disease." (PMID 40565155, 2025). "CD14+CD16+ monocytes are elevated in the patients with unstable angina and plaque rupture compared with the stable angina patients, and elevation of CD14++CD16+ monocytes is an independent predictor of cardiovascular events in subjects with high risk of coronary disease." (PMID 28961259, 2017). "Abnormally expressed CD14 and CD16 molecules on monocytes have been detected in coronary artery disease." (PMID 32922178, 2020). "Compared with healthy controls, coronary heart disease (CAD) patients show significantly upregulated plasma concentrations and mRNA expression of MCP1 in CD14+ monocytes." (PMID 31737059, 2019). "This study sought to investigate the impact of CD14++CD16+ monocytes on plaque vulnerability, as assessed by virtual histology intravascular ultrasound (VH-IVUS), as well as their relationship to fluctuating glucose levels in patients with asymptomatic coronary artery disease (CAD)." (PMID 28789689, 2017).
Insulin resistance (40 papers, 2010 to 2025). Increased resistance towards insulin, that is, diminished effectiveness of insulin in reducing blood glucose levels. "After the LPS is produced and released into the circulation, inflammatory response often occurs through LPS/CD14 system and subsequently causes body weight gain and insulin resistance." (PMID 29081799, 2017). "This hypothesis was supported by results from animal models whereby CD14-deficient mice were protected from insulin resistance and glucose intolerance when fed a high fat diet." (PMID 38817635, 2024). "This increase in circulating CD14 levels could reflect a pro-inflammatory status of women with pre-eclampsia after delivery and possible underlying risk of developing insulin resistance and type II diabetes mellitus." (PMID 32066653, 2020). "When evaluating insulin resistance there was a significant interaction in the association of fasting insulin with % CD14++CD16− (classical) monocytes (p = 0.0365) and HOMA-IR (p = 0.0403), due to a significant association in the other race category (p = 0.0383 and 0.0277, respectively)." (PMID 32528415, 2020). "Thus, it has been shown that chronic infusion of low-dose LPS commences obesity and insulin resistance in a CD14-dependent manner, suggesting a causative link between LPS and development of insulin resistance." (PMID 26751381, 2016). "While experimental animal models have demonstrated a role of CD14 signaling in insulin resistance, limited data are available on this question from human studies." (PMID 38817635, 2024). "Short-term high-fat high-calorie diet increases the expression of CD14 in skeletal muscle of healthy men accompanied by reduced markers of insulin signalling and development of insulin resistance." (PMID 38331723, 2024). "High amounts of soluble CD14 used to compete with membrane CD14 were proven to be effective in reducing adipocyte-mediated inflammation and insulin resistance but ineffective in reducing body weight." (PMID 23898465, 2013). "Inflammation induced by the infusion of bacterial lipopolysaccharides reduced glucose-induced insulin secretion and led to insulin resistance, and increase production of cytokines through a mechanism requiring the LPS receptor CD14." (PMID 21673955, 2011). "Additionally, CD14 knockout mice have been reported to exhibit reduced lipid storage and improved insulin resistance, accompanied by decreased immune cell infiltration in both hepatic and ATs." (PMID 39645040, 2024). "Although the connection between CD14 and metabolic regulation is partially understood, it has been observed that obese WT mice transplanted with Cd14−/− bone marrow exhibit resistance to the development of insulin resistance." (PMID 39645040, 2024). "CD14 could be examined in larger cohorts as a predictive marker of insulin resistance and type II diabetes mellitus among women with PE." (PMID 32066653, 2020). "CD14 has been reported to induced inflammation and insulin resistance in adipose tissue." (PMID 32876525, 2020). "Upon binding to the complex of CD14 and toll-like receptor 4 on the surface of innate immune cells, LPS can induce systemic inflammation, which eventually impairs insulin sensitivity and induces insulin resistance-related metabolic disorders." (PMID 22880019, 2012). "Similarly, the roles of toll-like receptors, CD14, and rho kinases in regulating insulin signaling and establishment of insulin resistance in response to chronic low-grade inflammation are well documented." (PMID 20064776, 2010). "Furthermore, TLR4/CD14 signaling can induce hepatic insulin resistance." (PMID 26751951, 2016). "Upon binding to the complex of CD14 and toll-like receptor 4 at the surface of innate immune cells, LPS can trigger the secretion of proinflammatory cytokines, which eventually impairs insulin sensitivity and induces insulin resistance-related metabolic disorders." (PMID 27036035, 2016).
Insulin resistance (continued). "CD14/TLR4 plays a vital role in the recognition of bacterial origin LPS and induces cascade response of inflammation reaction, which leads to insulin resistance." (PMID 34966475, 2021). "Several studies reported that insulin resistance and hepatic steatosis were suppressed in TLR4 and CD14 mutant mice." (PMID 28349245, 2017). "JZG may regulate CD14/TLR4 and TLR2 signaling pathways, improving inflammation and insulin resistance targeted at gut microflora." (PMID 34966475, 2021). "By binding to the Toll-like receptor-4 (TLR-4)–CD14 complex, Lipopolysaccharide (LPS) activates the immune system, interfering with the insulin receptor and leading to an increase in testosterone production resulting in PCOS and insulin resistance." (PMID 34357331, 2021). "The mechanism through which CD14 participates in the regulation of lipogenesis, adipose tissue inflammation, and insulin resistance is not known." (PMID 23898465, 2013). "Moreover, both CCR5 and CCR2 expression levels correlate significantly with CD14+/CD16+ monocyte subset, and metabolic abnormalities such as dyslipidemia and insulin resistance, have been also reported to promote an inflammatory phenotype in circulating monocytes." (PMID 22645407, 2012).